CDK4 (cyclin dependent kinase 4)
Diseases named in the same sentence as CDK4 in open-access papers (continued):
Sharing a sentence is not in itself a finding about the gene and the disease.
breast cancer (continued). "To date, few studies investigate targeted approaches for AI-resistant breast cancer such as the use of lapatinib, intermittent letrozole treatment, histone deacetylase (HDAC) inhibitors, cdk4/6 inhibitors, or co-targeting cdk2 and cdk4/6." (PMID 37049472, 2023). "Of note, the majority of participants in SANDPIPER (97.0%) were cyclin‐dependent kinase 4/6 (CDK4/6) inhibitor‐naïve given that they were randomized between 2015 and 2017, which coincided with the initial approvals of CDK4/6 inhibitors for HR+, HER2− breast cancer treatment." (PMID 36892268, 2023). "Other scholars have found that the combination of CDK4/6 and PI3K inhibition may prevent early adaptation to acquired resistance in breast cancer." (PMID 38037159, 2023). "CDK4/6 inhibitors have become game-changers in the treatment of estrogen receptor-positive (ER+) breast cancer, and in combination with endocrine therapy are the standard of care first-line treatment for ER+/HER2-negative advanced breast cancer." (PMID 37035239, 2023). "There were a total of 220 patients with metastatic HR+/HER2-negative breast cancer with prior progression on AI and any CDK4/6 inhibitors." (PMID 37860199, 2023). "In terms of other agents, previous findings have shown that dual CDK4 and CDK6 inhibitors could sensitize HER2-targeted therapies and delay tumor recurrence in HER2+ breast cancer models." (PMID 37258523, 2023). "Multimodal treatment with local therapy remains the mainstay of the treatment; however, data concerning the safety and efficacy of such an approach in breast cancer patients treated with CDK4/6i and radiotherapy are lacking." (PMID 36902831, 2023). "“CYCLIN_D1.KE.V1.DN” gene signature includes genes downregulated in MCF-7 breast cancer cells heterogeneously over-expressing a mutant form of Cyclin D1 (K112E) lacking the ability to activate cyclin-dependent kinase 4 (CDK4)." (PMID 37700842, 2023). "The dependency evaluation of the cell lines with SCRIB, VANGL2 and NOS1AP amplifications with CRISPR and RNAi revealed several genes involved in breast cancer pathogenesis, such as FOXA1, ERBB2, PIK3CA and CDK4, to be among the top preferential essential genes." (PMID 36675340, 2023). "A recent study declared that CDK4/CDK6 inhibitors (8, 9, and 10) might impede SARS-CoV-2 infection in breast cancer females." (PMID 36851782, 2023). "Currently, breast cancer patients receive different kinds of therapy, with monoclonal antibodies against human epidermal growth factor receptor 2 (HER2) and cyclin-dependent kinase 4/6 (CDK4/6) inhibitors being the most commonly used targeted agents." (PMID 38023235, 2023). "The CDK4/6 inhibitors palbociclib, ribociclib, and abemaciclib are each indicated in the first-line for recurrent unresectable or metastatic ER+/HER2-breast cancer in combination with an aromatase inhibitor (AI), with concurrent ovarian function suppression for pre-menopausal women." (PMID 37035239, 2023). "The vast majority of hormone positive and HER2 negative advanced breast cancers can be controlled well by endocrine therapy combined with the groundbreaking use of CDK4/6 inhibitors in the metastatic first-line setting." (PMID 37886029, 2023). "Cyclin-dependent kinase 4/6 (CDK4/6) has now become a promising strategy for HER2-positive, HR-positive breast cancer treatment as it is the downstream of the estrogen receptor (ER) and HER2 pathways, as well as many other cellular pathways inducing resistance to HER2-targeted therapies." (PMID 35321427, 2022). "Previous findings suggested that the combination of anti-HER2 agent, CDK4/6 inhibitor and endocrine therapy could be synergistic in HER2-positive, HR-positive breast cancer." (PMID 35321427, 2022). "While CDK4/6 inhibitors can induce a senescent-like state, it is not clear that these agents can directly kill luminal breast cancer cells." (PMID 35248122, 2022). "CDK8, CDK7, CDK4, and CDK1 predicted unfavorable outcomes in luminal A breast cancer patients." (PMID 35628286, 2022).
breast cancer (continued). "There are no data directly comparing a CDK4/6 inhibitor to a PARP inhibitor in gBRCAm carriers with breast cancer." (PMID 35396508, 2022). "The current standard of care for metastatic ER-positive/Her2 negative breast cancer utilizes the combination of either the estrogen receptor degrader Fulvestrant or aromatase inhibitors such as Letrozole with CDK4/6 inhibitors such as Palbociclib." (PMID 36077830, 2022). "In vivo, resistance to CDK4/6 and to anti-HER2 treatment inhibitors can be reversed by combination with anti-FGFR drugs, such as lucitanib or erdafitinib; this indicates the importance of targeting different pathways in breast cancer." (PMID 35193394, 2022). "There were several hot targeting drugs in breast cancer treatment, comprising the HER-2-targeting monoclonal antibody (mAb), CDK4/6 inhibitor, poly ADP-ribose polymerase (PARP) inhibitor, PI3K/AKT/mTOR pathway inhibitor, ER targeting drugs, and aromatase inhibitor (AI)." (PMID 35402243, 2022). "For example, poor response to CDK4/6 inhibitors has been observed in patients with coexisting FGFR1 amplification in hormone receptor-positive breast cancer and dual HER2-targeted therapy in HER2-positive breast cancer." (PMID 35193394, 2022). "Despite the biological and therapeutic relevance of CDK4/6 for the treatment of HR+, HER2- advanced breast cancer, the detailed mode of action of CDK4/6 inhibitors is not completely understood." (PMID 36446794, 2022). "In recent years, targeting agent therapy has also become one of the selective breast cancer treatment strategies, including anti-HER-2 drugs, CDK4/6 inhibitor, poly ADP-ribose polymerase inhibitor, PI3K/AKT/mTOR pathway inhibitor, ER targeting drugs, and aromatase inhibitor." (PMID 35402243, 2022). "Overall, the drug was well tolerated, and the toxicity profile is comparable with other nonendocrine-targeted therapies in breast cancer, such as CDK4/6 inhibitors." (PMID 35881485, 2022). "Another study has shown up-regulation of CDK4/6 and pRb levels in HER2 + breast cancer samples." (PMID 36266723, 2022). "Our results suggested that miR-885-3p could suppress the proliferation of breast cancer cells, partially by suppressing the expression levels of CDK2/CCNE1 and CDK4/6/CCND1 and arresting the cell cycle in the G0/G1 phase." (PMID 35383130, 2022). "Repression of CDK4 and CDK6 levels by miR-138 has been demonstrated in breast cancer cell lines." (PMID 34937878, 2022). "Additionally, loss-of-function alterations in RB1, predicted to contribute to CDK4/6 inhibitor resistance, were observed in 13.3% (6/56) of CDK4/6 inhibitor-treated HR+ HER2- breast cancer patients." (PMID 35486650, 2022). "Ongoing and future clinical trials will evaluate the potential and applicability of combining endocrine therapy with growth factor inhibitors or CDK4/6 inhibitors to overcome intrinsic resistance and prevent or delay acquired resistance in patients with ER+/HER2+ breast cancer." (PMID 35613334, 2022). "In the dose-expansion phase, patients with CDK4/6i-treated breast cancer, or KRAS-mutant (KRASmut) non-small-cell lung cancer (NSCLC) received the MTD." (PMID 36291780, 2022). "CDK4/6 inhibitors are currently used to treat hormone receptor (HR) positive/human epidermal growth factor receptor 2 (HER2) negative breast cancer." (PMID 36530984, 2022). "The addition of the CDK4/6 inhibitors palbociclib, ribociclib, and abemaciclib to an aromatase inhibitor were studied in postmenopausal HR‐positive/HER2‐negative advanced breast cancer in the first‐line setting in PALOMA‐2, MONALEESA‐2, and MONARCH‐3 trials, respectively." (PMID 36254250, 2022). "In this study, we demonstrate that CDK4/6i and radiotherapy led to an RB-dependent increase in both radiosensitization and breast cancer cell death in multiple, nonoverlapping ER+ and TNBC models in vitro and in vivo." (PMID 34932500, 2022).
breast cancer (continued). "Preclinical models showed that CDK4/6 inhibitors could sensitize HER2-targeted therapy and delay tumor recurrence in HER2+ breast cancer." (PMID 35321427, 2022). "Since T-DXd has made a breakthrough in HER2-positive breast cancer, anti-HER2 ADC combined with CDK4/6 inhibitor and endocrine therapy may be the future exploring direction of HR-positive/HER2-positive breast cancer." (PMID 35321427, 2022). "The addition of a CDK4/6 inhibitor to endocrine therapy prolonged progression-free survival (PFS) and overall survival (OS) in patients with advanced or metastatic HR+/HER2– breast cancer." (PMID 36291780, 2022). "In breast cancer cells, concurrent administartion of CDK2 and CDK4/6 inhibitiors could reverse palbociclib resistance through increasing cell senescence." (PMID 36266723, 2022). "For stage IV HR+/HER-2 negative breast cancer patients, CDK4/6 inhibitors are used in the treatment of these patients; however, only palbociclib and ribociclib are authorized in the formulary so far." (PMID 36612831, 2022). "The specificity of the CDK4/6Is, and evidence for increased CDK activity in HR+ breast cancers suggested the potential utility of CDK4/6Is in combination with endocrine therapy for therapy-specific breast cancer subtypes." (PMID 36358806, 2022). "Next, we utilized isogenic models of breast cancer to explore how the presence or absence of RB led to changes in intrinsic cellular radiosensitivity and CDK4/6 inhibitor–mediated radiosensitization in ER+ and TNBC." (PMID 34932500, 2022). "For example, CDK4/6 inhibitors, such as palbociclib, abemaciclib, and ribociclib, are used clinically to treat oestrogen receptor‐positive (ER+) and human epidermal growth factor receptor 2‐negative (HER2−) breast cancer." (PMID 35674109, 2022). "Given that RB is a key mediator of the senescence program, it is also not surprising that pharmacologic CDK4/6 inhibition induces a phenotype resembling senescence in luminal breast cancer cells." (PMID 35248122, 2022). "Biomarkers are essential for precision oncology, and despite widespread research efforts, no clinically validated biomarkers beyond breast cancer subtype have been established to guide the use of CDK4/6 inhibitors." (PMID 36176758, 2022). "Although it has been reported that CYCLIN D2 expression compensates for loss of CYCLIN D1 expression in Wnt-driven mammary tumors, neither CDK2 nor CDK6 appear to compensate for the absence of CDK4 expression." (PMID 36051751, 2022). "There are no safety data for combining a PARP inhibitor and a CDK4/6 inhibitor for patients with early stage breast cancer, and this is not recommended." (PMID 35396508, 2022). "In addition, we assessed the effects of PI3K and Cyclin-Dependent-Kinase-4/6 (CDK4/6) inhibitor combinations on the HPV+/HPV− CU-OP lines and revealed positive synergistic effects similar to that for certain breast cancer types." (PMID 36612094, 2022). "In addition, western blotting indicated that miR-885-3p suppressed the progression of breast cancer cells by downregulating the expression level of PCNA and the expression levels of CDK2/CCNE1 and CDK4/6/CCND1 (Student’s t test, p < 0.05)." (PMID 35383130, 2022). "According to results of randomised controlled trials, when CDK4/6 inhibitor added to letrozole in the first line treatment of HR positive Her2 negative advanced breast cancer patients, median PFS times were doubled and also median OS was improved." (PMID 35525929, 2022). "Although the efficacy of combining HT and CDK4 and CDK6 inhibitor in patients with ESR1+/HER2− breast cancer, the promising benefit of CDK4 and CDK6 drug inhibitors in other neoplasms has not been extensively tested." (PMID 34445095, 2021). "Here, we show that triple inhibition with fulvestrant, CDK4/6i and AKT inhibitor (AKTi) durably impairs growth of breast cancer cells, prevents progression and reduces metastasis of tumor xenografts resistant to CDK4/6i-fulvestrant combination or fulvestrant alone." (PMID 34433817, 2021).
breast cancer (continued). "A network meta-analysis showed that the combinations of CDK4/6 inhibitors, such as PAL, ribociclib, and abemaciclib, with high-dose FUL were among the most effective treatment options for advanced ER+ breast cancer as reflected in overall and progression-free survival." (PMID 33980285, 2021). "Current NCCN and Japanese Breast Cancer Society guidelines do not provide recommendations regarding optimal breast cancer treatment sequences or subsequent treatment options following CDK4/6 inhibitor therapy." (PMID 33085032, 2021). "In a subset of patients with cancer (not breast cancer) with sensitizing cell-cycle gene alterations treated with CDK4/6 inhibitors, we show examples of responders." (PMID 33427211, 2021). "CDK4/6 inhibitors (CDK4/6i), such as Palbociclib, Ribociclib and Abemaciclib, have recently gained FDA-approval and shown success in the treatment of advanced metastatic hormone receptor-positive (HR+)/HER2-negative breast cancer." (PMID 34828525, 2021). "CDK4 and CDK6, therefore, emerged as viable therapeutic targets, and evaluation of CDK4 and 6 inhibitors in combination with other therapies is an area of active investigation that is changing the treatment landscape for HR+, HER2- advanced breast cancer." (PMID 35223458, 2021). "Importantly, the addition of a PDK1 inhibitor to CDK4/6 inhibitor treatment reversed the resistance in ER+ breast cancer cell lines, and both PDK inhibition, as well as PI3K inhibition, potentiated the effect of a CDK4/6 blockade in xenograft models." (PMID 33535617, 2021). "Three selective CDK4/6 inhibitors (palbociclib, abemaciclib, and ribociclib) have been FDA approved for the treatment of metastatic ER-positive (ER+) breast cancer patients in combination with endocrine therapy given their proved ability to increase progression-free survival." (PMID 33599863, 2021). "There are no established molecular biomarkers for patients with breast cancer receiving combination endocrine and CDK4/6 inhibitor (CDK4/6i)." (PMID 32940689, 2021). "Notably, in keeping with previous reports, we found that CDK6 silencing was the top scoring genetic event for enhancing efficacy of CDK4/6i, and RB1 depletion was the top hit for promoting resistance in breast cancer cells to CDK4/6i." (PMID 34508104, 2021). "Consistently, a combinatorial drug screen of 42 compounds found that CDK4/6 inhibition exhibits the most significant synergism with PI3K inhibitors (BYL719 and GDC-0941) in a panel on PI3K-mutant breast cancer cell lines (T47D, MCF7, and MDA-MB-453) resistant to PI3K inhibition." (PMID 33809714, 2021). "Specifically, seven patients from this trial were treated with endocrine therapy with or without CDK4/6 inhibitors for metastatic HR+/HER2- breast cancer." (PMID 34439167, 2021). "Therefore, the CDK4/6–USP51–ZEB1 axis enhances EMT-mediated metastasis in breast cancer, providing a new target for advanced breast cancer management." (PMID 34575114, 2021). "Gene amplification is the most frequent genetic alteration in breast cancer with MYC, CCND1, epidermal growth factor receptor (EGFR), fibroblast growth factor receptor (FGFR), CDK4, and MDM2 being the genes most frequently amplified in primary and recurrent breast tumors." (PMID 33996588, 2021). "Currently, there are several ongoing clinical trials evaluating triple combination therapy consisting of endocrine therapy, CDK4/6i, and other inhibitors of the PI3K/AKT/mTOR pathway in ER+ advanced breast cancer following progression on a CDK4/6i regimen (NCT02871791, NCT02732119)." (PMID 34433817, 2021).
breast cancer (continued). "Indeed, the combination of mTORC1 inhibitors and CDK4/6 inhibitors had a potent activity across a large number of patient-derived models of PDAC and breast cancer." (PMID 34360912, 2021). "There are currently multiple on-going clinical trials assessing the combination of checkpoint blockade with PARP inhibitors (NCT03594396, NCT02849496) and CDK4/6 inhibitors (NCT02778685, NCT02779751, NCT0314728, NCT03147287, NCT03573648, NCT03294694) in HR+ breast cancer." (PMID 34135901, 2021). "To gain more insights into which genes involved in cell cycle regulation may modulate the anti-tumor efficacy of CDK4/6i in breast cancer, we performed CRISPR/Cas9-mediated genetic screen in MCF7 and MDA-MB-231 breast cancer cell lines." (PMID 34508104, 2021). "Importantly, due to their significant efficacy, CDK4/6 inhibitors are now recommended in the clinical practice, in the first-line or second-line setting in women with HR+, HER2- breast cancer, in combination with hormonal or targeted therapies." (PMID 33498502, 2021). "Although this data suggests a role of increased WEE1 in ER+ breast cancer progression, further studies are needed to determine whether increased WEE1 expression correlate with resistance to antiestrogens or CDK4/6 inhibitors." (PMID 34277427, 2021). "In early breast cancer, data were lacking about the predictive role of gene expression signatures towards CDK4/6 inhibitors efficacy." (PMID 34638325, 2021). "Palbociclib, a CDK4/6 inhibitor, is currently approved for advanced breast cancer and in phase III clinical trials; P276-00, a selective CDK4 inhibitor (79.7% cytotoxicity), has shown anti-proliferative effects against other cancers, but too has not been assessed in neuroblastoma." (PMID 34722256, 2021). "On the one hand, we found that knockdown of PRMT1 decreased Cyclin E2, Cyclin B1 and CDK4 expression in MCF7 and MDA-MB-231 breast cancer cells; on the other hand, we also confirmed that ectopic expression of PRMT1 increased the expression of these mentioned proteins." (PMID 34775498, 2021). "Some inhibitors of CDK4/6 have been approved for use in combination with nonsteroidal aromatase inhibitors for the first-line treatment of breast cancer in postmenopausal women, and PFS can be increased by 40-45%." (PMID 33952716, 2021). "Here, we assessed the efficacy of fulvestrant, CDK4/6i and AKTi as single agents and in different combinations in MCF-7 and T47D breast cancer cell lines exhibiting acquired resistance to combined CDK4/6i and fulvestrant treatment (MPF-R and TPF-R, respectively)." (PMID 34433817, 2021). "At present, preclinical or clinical studies have not found that a single CDK4/6 inhibitor can successfully inhibit HER2+/HR+ breast cancer." (PMID 34977029, 2021). "Indeed, miR-122-5p inhibitors indicated a major effect of miR-122-5p on the regulation of key antiapoptotic proteins Bcl-2 and cyclin-dependent kinases (CDK2, CDK4 and CDK6) in drug-resistant breast cancer cells in response to RSV." (PMID 34444715, 2021). "Following promising clinical outcomes, palbociclib was FDA approved for the treatment of HR-positive, HER2-negative breast cancer in 2015, irrespective of CDK4/6 alteration status." (PMID 34025662, 2021). "For example, a recent report demonstrated that treatment of ER+ breast cancer and KRAS-mutant NSCLC cells with eIF4A inhibitor could inhibit cell cycle feedback response and drug-resistance to CDK4/6 inhibitor treatment." (PMID 33414445, 2021). "Though this work has not been repeated in ER+ breast cancer cells, it is possible that resistance to CDK4/6 inhibitors in ER+ breast cancer is the result of increased lysosomal segregation." (PMID 34830174, 2021). "CompLEEment-1 is a phase 3b trial in an expanded patient population with hormone receptor-positive (HR +), human epidermal growth factor receptor-2–negative (HER2–) advanced breast cancer (ABC), the largest current trial of cyclin-dependent kinase 4 and 6 inhibitors in ABC." (PMID 34414532, 2021).